Y_RNA (Y RNA )
Gene: Miscellaneous RNA gene on chromosome 3 (38,014,568 to 38,014,669, forward strand). Ensembl gene ENSG00000200579.
Homologues: Orthologues: chimpanzee Y_RNA (99% identical). Paralogues in human: Y_RNA (91% identical), Y_RNA (90% identical), Y_RNA (89% identical), RNY3 (88% identical), Y_RNA (88% identical), RNY3P1 (87% identical), Y_RNA (87% identical), Y_RNA (86% identical), RNY3P14 (85% identical), Y_RNA (85% identical), Y_RNA (84% identical), RNY3P11 (83% identical), and 98 more.